CELF1 (CUGBP Elav-like family member 1)
Diseases named in the same sentence as CELF1 in open-access papers (continued):
Sharing a sentence is not in itself a finding about the gene and the disease.
breast carcinoma (continued). "As our analysis above shows that CELF1 plays a vital role in lumina A breast cancer patients, we then proceeded to determine whether cancer cell lines with heightened CELF1 levels exhibit unique functionalities in contrast to cell lines with reduced CELF1 expression." (PMID 41306913, 2025). "Although the power of our analysis of CELF1 expression as a prognostic marker with regard to disease outcome was handicapped by the high median value of CELF1 score observed in breast cancer tumour tissues, further investigation in larger annotated tissue sets may solidify this association." (PMID 27869122, 2016). "In addition to reports of involvement in breast cancer and leukemia development, the CELF1 gene may also play a significant role in tumorigenesis and the deterioration of certain tumors, which is also confirmed by the results in our present study." (PMID 24237593, 2013). "In the previous study, we explored the influence of CELF1 on the alternative splicing of INSR and observed a shift in its oncogenic effects in breast cancer; these effects were found to differ among various molecular subtypes." (PMID 41306913, 2025). "Our previous study revealed that CELF1 exerts its influence by modulating the LIP/LAP molar ratio, thereby controlling the diverse mRNA splicing profiles of INSR in breast cancer cells and affecting cell aggressiveness." (PMID 41306913, 2025). "From our findings, we propose a model in which under TGF-β induction, CELF1 functions downstream of PKCα and PKCε to drive EMT and metastasis in breast cancer cells." (PMID 39343007, 2024). "CELF1 is necessary and sufficient for both mesenchymal transition and metastatic colonization, and CELF1 protein, but not mRNA, is significantly overexpressed in human breast cancer tissues." (PMID 27869122, 2016). "Given the post-translational mode of regulation of CELF1 expression, it is perhaps unsurprising that examination of TCGA data sets revealed neither significant variations in relative CELF1 mRNA expression among different breast cancer subtypes nor in comparisons of tumour with normal tissue." (PMID 27869122, 2016). "On the contrary, CELF1 functions as a negative translation regulator via binding to the 5’ UTR of p21 mRNA in the mouse lens cell line and p27 mRNA in the breast cancer cell." (PMID 36240182, 2022). "Interestingly, Celf1-mediated translational repression of p27Kip1, potentially through interference of an internal ribosome entry site (IRES) in its 5’UTR, is observed in cultured breast cancer cells, but has never before been described in developing tissue." (PMID 29565969, 2018).
glioma (10 papers, 2015 to 2025). A benign or malignant brain and spinal cord tumor that arises from glial cells (astrocytes, oligodendrocytes, ependymal cells). "In glioma cells, CELF1 is bound to suppress the expression of endogenous CDKN1B and attenuates translation initiation via interaction with the overexpression region of CDKN1B." (PMID 38443798, 2024). "Elevated expression of CELF1 has been found to correlate with unfavorable overall survival outcomes in glioma patients." (PMID 38443798, 2024). "CELF1 promotes glioma cell proliferation by decreasing the expression levels of CDKN1B within the glioma microenvironment." (PMID 38443798, 2024). "In an initial investigation using dual luciferase reporter gene assays, it was confirmed that miR-330-3p directly targets CELF1,resulting in the downregulation of CELF1 expression and subsequently inhibiting the proliferation and migration of glioma cells." (PMID 38443798, 2024). "This tumor suppressor is reported to have low expression in glioma tissues and cells, and it is able to prevent proliferation and migration by directly binding to CELF1 and suppressing its expression." (PMID 34681716, 2021). "CELF1 was abundantly expressed in the glioma tissues, and CELF1 expression was repressed by miR-330-3p to inhibit proliferation and migration of glioma cells." (PMID 34697393, 2021). "In glioma, the increased expression of CELF1 is positively correlated with glioma grading and inversely correlated with patient survival, making it a novel prognostic predictor for glioma patients." (PMID 34681716, 2021). "SiRNA (small-interfering RNA)-mediated knockdown of CELF1 inhibits the glioma cell cycle progression and proliferation." (PMID 34681716, 2021). "Several studies have revealed that CELF1 demonstrates frequent upregulation in glioma, oral squamous-cell carcinomas, and hepatocellular carcinoma, and its oncogenic properties make it a crucial target for influencing cell proliferation and growth and precisely regulating the cell cycle." (PMID 41306913, 2025). "In gliomas, CELF1 is upregulated and promotes cell proliferation by inhibiting CDKN1B." (PMID 40781108, 2025). "Most notably, compared to the expression of flanking exons in UMSCC-74B cells, CELF1 depletion caused a 5-fold increase in the exclusion of exon 49 in COL16A1 (collagen type XVI), which encodes an extracellular matrix protein involved in oral cancer cell proliferation and glioma cell invasion." (PMID 26498364, 2015). "In glioma cells, the tumor suppressor CDKN1B (Cyclin Dependent Kinase Inhibitor 1B) has been identified as a CELF1 target." (PMID 34681716, 2021). "Some studies have reported that CELF1, DDX17 and ZNF326 are overexpressed in glioma." (PMID 34482818, 2021).
hepatocellular carcinoma (8 papers, 2013 to 2025). A malignant tumor that arises from hepatocytes. "BACE1-AS enhanced the invasion and metastasis of hepatocellular cancer cells by mediating the miR-377-3p/CELF1 axis." (PMID 40488465, 2025). "We thus crossed the DEK-modulated transcriptome with information available in ENCODE for CELF1 (i.e., in K562 leukemia cells, ENCSR605MFS; and in the HepG2 hepatoma cell line, ENCSR695XOD)." (PMID 29269732, 2017).
cataract (7 papers, 2011 to 2026). Partial or complete opacity of the crystalline lens of one or both eyes that decreases visual acuity and eventually results in blindness. "Among the DEGs, 43 genes, including Celf1, have previously been linked to cataracts in humans or animal models as per Cat-Map." (PMID 37048143, 2023). "Deficiency or alteration of several RNA-binding proteins, including the conserved RBP Celf1 (CUGBP Elav-like family member 1), has been described to cause lens defects and early onset cataracts in animal models and/or humans." (PMID 37048143, 2023). "While Cat-Map allows identification of a subset of DEGs that are known to be associated with cataracts, to gain further insights into the impact of Celf1 deficiency on transcripts relevant to lens biology, comparative analysis was performed using iSyTE." (PMID 37048143, 2023). "Previous studies have also shown that CELF1 was associated with cataract by functioning as an RNA binding protein." (PMID 35287612, 2022). "Conditional deletion of Celf1 gene in the mouse lens causes early-onset cataracts." (PMID 41542625, 2026). "Mouse models of Celf1 deficiency exhibit cataracts and other pathologies." (PMID 37048143, 2023). "Importantly, the present analyses identify as yet unappreciated and novel high-priority candidates in the lens for defining new pathways involved in lens biology (e.g., Ell2 and Prdm16) that likely also contribute to the cataracts resulting from Celf1 deficiency." (PMID 37048143, 2023). "Together, these data have defined the alterations in lens transcriptome caused by Celf1 deficiency, in turn uncovering downstream genes and pathways (e.g., structural constituents of eye lenses, lens fiber cell differentiation, etc.)associated with lens development and early-onset cataracts." (PMID 37048143, 2023). "In human, CELF1 is indirectly implicated in cataract through Myotonic Dystrophy, type 1 (DM1), a multisystem disorder that causes cataracts among other symptoms." (PMID 41542625, 2026). "Knockout of mammalian homologs of cataract-associated genes, such as TMEM114, CHRLD1, SIPAL3, or CELF1, results in ocular phenotypes loosely associated with cataracts." (PMID 41210874, 2025). "Celf1 germline knockout mice and lens conditional knockout (Celf1cKO) mice develop fully penetrant cataracts in early postnatal stages." (PMID 37048143, 2023). "In agreement with previous studies, we provided evidence that elevated CELF1 may also affect cataract pathogenesis and lens development." (PMID 35287612, 2022). "These CELF1-targeted genes suggest that CELF1 might involve in lens development or cataract pathogenesis by changing expression levels of TFs, which need to be clarified in future." (PMID 35287612, 2022). "In this study, we observed that MMP9 was upregulated in both CELF1-OE SRA01/04 cells and mouse E14.5 samples, suggest it might affect lens development or cataract pathogenesis." (PMID 35287612, 2022). "Additionally, an absence of Celf1 is expected to lead to changes to the lens transcriptome that result in lens defects and cataracts." (PMID 37048143, 2023). "However, the direct molecular mechanisms by which the lack of CELF1 results in cataracts remain unclear." (PMID 41542625, 2026).
colorectal cancer (7 papers, 2017 to 2025). A primary or metastatic malignant neoplasm that affects the colon or rectum. "Previous study have demonstrated that RNA-binding protein CELF1 targeted ETS2 in colorectal cancer, contributing to tumor cell migration, invasion and promotion of chemoresistance." (PMID 36991138, 2023). "Loss of CELF1 expression downregulated the MAPK signaling pathway and promoted colorectal cancer cell proliferation and chemoresistance." (PMID 29728583, 2018). "Furthermore, CELF1 enhances cell migration, invasion, and chemoresistance in colorectal cancer by targeting ETS2." (PMID 40781108, 2025). "Former investigations revealed that CELF1 could enhance cell migration, invasion, and chemoresistance in colorectal cancer by targeting ETS228." (PMID 34697393, 2021). "RNA-binding protein CELF1 contributes to migration, invasion, and chemotherapy resistance by targeting ETS2 in colorectal cancer and could be a potential diagnostic and prognostic marker." (PMID 32873282, 2020). "CELF1 and ETS2 are both upregulated in colorectal cancer cells and can promote tumorigenesis." (PMID 34681716, 2021). "CELF1/lncRNA combinations with strong affinity have also been seen in colorectal cancer, where CELF1-TNBL aggregates occur in non-perinucleolar areas upon demethylation events." (PMID 34681716, 2021).
liver fibrosis (7 papers, 2016 to 2025). "Consequently, CELF1 presents itself as a promising therapeutic target for the management of hepatic fibrosis and its associated conditions." (PMID 38443798, 2024). "These encouraging findings highlight the potential of developing CELF1 RNA-binding inhibitors as a novel therapeutic strategy for liver fibrosis." (PMID 38443798, 2024). "Compound 27 was shown to effectively disrupts CELF1’s interaction with RNA, thereby inhibiting the activation of hepatic stellate cells (HSCs)—a key event in the progression of liver fibrosis." (PMID 39456596, 2024). "This compound represents a significant advancement in the pharmacological targeting of this RBP, providing a promising new avenue for treating liver fibrosis and potentially other related diseases where CELF1 plays a detrimental role." (PMID 39456596, 2024). "CELF1 has been identified as a facilitator in the activation of hepatic stellate cells (HSCs) and the advancement of hepatic fibrosis by suppressing the expression of anti-fibrotic IFN-γ mRNA." (PMID 38443798, 2024). "In studies involving mice, researchers have observed a targeted modulation of CELF1 expression in activated hematopoietic stem cells, aiming to mitigate liver fibrosis." (PMID 38443798, 2024). "Recently, exciting clues have emerged in CELF1 research, discovering a small molecule inhibitor (compound 1) that effectively inhibits CELF1 binding activity and is considered a potential therapeutic approach for liver fibrosis." (PMID 38443798, 2024). "CELF1 is an RBP that was found to play a role in a variety of cardiovascular diseases including myotonic dystrophy and dilated cardiomyopathy, but also in liver fibrosis (K.‐T." (PMID 39668490, 2024). "Hepatic stellate cell activation is a key step liver fibrosis and was modulated by compound 27 by stabilizing IFN‐γ RNA which is normally degraded by CELF1 as well as downregulating ACTA2 and COL1A1 mRNA." (PMID 39668490, 2024).
lung carcinoma (7 papers, 2013 to 2025). "For example, CELF1 is overexpressed in gastric and lung cancers, and knocking down CELF1 significantly inhibits tumor cell proliferation." (PMID 40781108, 2025). "Recently, CELF1 was shown to affect E-cadherin levels in A549 lung cancer cells, however, the mechanism of CELF1 regulation of E-cadherin remains to be elucidated." (PMID 26498364, 2015). "In this study, CELF1 silencing by siRNA lentiviral-mediated transfection strongly reduced survival rates in lung cancer cells, likewise the number and size of lung cancer cell colonies." (PMID 25593996, 2014). "Colony formation assays revealed a reduction in the number and size of lung cancer cell colonies from CELF1 knockdown." (PMID 24237593, 2013). "Reports in the literature have suggested that upregulation of CELF1 increased the turnover of oncogenes related to the proliferation of lung cancer cells." (PMID 24237593, 2013). "CELF1 mRNA expression was determined in lung cancer and normal tissues, and the relationship between the expression level of CELF1 and clinicopathological parameters was evaluated." (PMID 24237593, 2013). "The expression of CELF1 was higher in human lung cancer tissues compared with the normal lung tissue." (PMID 24237593, 2013). "Together these results indicate that CELF1 plays an important role in the growth progression of lung cancer cells." (PMID 24237593, 2013). "Our research primarily focused on the effect of CELF1 knockdown on the viability of lung cancer cells." (PMID 24237593, 2013). "From these results, we can conclude that CELF1 can affect the growth of lung cancer cells and plays an important role in the tumor development process." (PMID 24237593, 2013). "This study investigated the expression levels of CELF1 in lung cancer tissues and the biological function of CELF1 in lung cancer cells." (PMID 24237593, 2013). "Here we investigated the relationship between CELF1 expression and lung cancer clinicopathological factors at the RNA level and clarified the physiological impact of CELF1 on lung cancer cell growth at the cellular level." (PMID 24237593, 2013). "Lung cancer cells tend to form large cell colonies while in culture; therefore, we next evaluated the effect of CELF1 silencing on the colony forming ability of lung cancer cells." (PMID 24237593, 2013). "Further research on the molecular mechanisms of the CELF1 gene is required, particularly in identifying CELF1-interacting proteins, elucidating the molecular mechanisms underlying its biological effects, and determining whether it plays a guiding role in the treatment of lung cancer." (PMID 24237593, 2013). "As shown in the results, the expression of CELF1 was higher in human lung cancer tissues compared with normal tissues." (PMID 24237593, 2013). "The effect of CELF1 knockdown on lung cancer cell survival was analyzed using a MTT assay performed over a five-day time course." (PMID 24237593, 2013). "Results showed that the relative expression levels of CELF1 were higher in lung cancer tissues compared with the normal tissues." (PMID 24237593, 2013). "Next, CELF1 mRNA and protein levels in A549 and H1299 lung cancer cells were evaluated by real time PCR and western blot, respectively." (PMID 24237593, 2013). "In addition, reduction of CELF1 using siRNA in lung cancer cells decreased the proliferative rate and the capacity of the lung cancer cells to form colonies." (PMID 26498364, 2015). "A previous report identified a correlation between the expression of CELF1 and human lung cancer." (PMID 24237593, 2013). "Moreover, A549 and H1299 lung cancer cells also exhibited CELF1 expression in mRNA and protein level." (PMID 24237593, 2013). "Interestingly, upon knockdown of CELF1, the survival rates and colony forming ability of lung cancer cells were markedly reduced, indicating pivotal roles of CELF1 in the survival of lung cancer cells." (PMID 24237593, 2013).
lung carcinoma (continued). "The biological function of CELF1 in A549 and H1299 lung cancer cell lines growth was examined." (PMID 24237593, 2013). "As yet, there is little knowledge of CELF1 expression and biological function in lung cancer." (PMID 24237593, 2013). "Moreover, the expression levels of CELF1 in lung cancer tumors varied depending on tumor grade." (PMID 24237593, 2013). "Moreover, CELF1 knockdown markedly reduced the survival rate of lung cancer cells." (PMID 24237593, 2013). "In summary, CELF1 may have significant roles in the progression of lung carcinoma." (PMID 24237593, 2013). "We speculate that CELF1 may also play an important role in lung cancer proliferation." (PMID 24237593, 2013). "The CELF1expressing lung cancer cells were then infected with lentivirus containing CELF1 shRNA or non-silencing control shRNA, and successful infection was confirmed by green fluorescence of infected cells." (PMID 24237593, 2013). "Together these data indicate that CELF1 expression is not related to postoperative survival in lung cancer patients." (PMID 24237593, 2013). "So far there is no literature reporting the biological function of CELF1 gene in lung cancer cell." (PMID 24237593, 2013). "Whether the expression of the CELF1 gene is related to the proliferation of human lung cancer has not been investigated." (PMID 24237593, 2013).
Myotonia (6 papers, 2016 to 2023). An involuntary and painless delay in the relaxation of skeletal muscle following contraction or electrical stimulation. "Interestingly, a similar observation was made in the 5-313+/− mouse model of DM1, in which loss of CELF1 preserves muscle function but does not improve myotonia, thus suggesting that Drosophila is a reliable model for studying CELF1 involvement in DM1." (PMID 29716962, 2018). "The reverse balance of MBNL1 and CELF1 in DM1 leads to the mis-splicing of these pre-mRNAs, collectively explaining myotonia, diabetes and reduced myocardial function manifested in patients." (PMID 29716962, 2018).
oral squamous cell carcinoma (6 papers, 2015 to 2025). "The depletion of CELF1 reduces proliferation and increases apoptosis in oral squamous cell carcinoma where CELF1 associates directly with the 3′UTR of BAD (BCL2 Associated Agonist Of Cell Death), BAX (BCL2 Associated X, Apoptosis Regulator) and JunD mRNAs and mediates their rapid decay." (PMID 34681716, 2021). "No significant cell death was observed even at late times after CELF1 depletion, in contrast to HeLa or cells from laryngeal or oral squamous cell carcinoma, where CELF1 was found to control pro-apoptotic genes." (PMID 29269732, 2017). "Here, to provide a global prospective of CELF1 regulation of oral squamous cell carcinoma, we performed RNA-sequencing in oral cancer cells and CELF1 overexpression analysis in non-malignant human oral keratinocytes." (PMID 26498364, 2015). "Altogether, these data support CELF1 as a major contributor to oral squamous cell carcinoma tumorigenesis." (PMID 26498364, 2015). "As for the transcriptomics level, researchers from Medical University of South Carolina validated that at least in oral squamous cell carcinoma, the alteration of the gene expression of COL16A1 may promote tumor growth via interacting with the RNA-binding protein CELF1." (PMID 35155435, 2022).